HIF1A (hypoxia inducible factor 1 subunit alpha)
Diseases named in the same sentence as HIF1A in open-access papers (continued):
Sharing a sentence is not in itself a finding about the gene and the disease.
ischemic cardiomyopathy (5 papers, 2012 to 2025). Ischemic cardiomyopathy is a cardiomyopathy in which a weakness in the muscle of the heart due to inadequate oxygen delivery to the myocardium with coronary artery disease being the most common cause. "This is similar to the role of HIF-1α in ischemic cardiomyopathy." (PMID 36172572, 2022). "However, further studies are required to know the precise role of HIF-1α on myocardial LRP1 overexpression in ischemic cardiomyopathy." (PMID 22873206, 2012). "MIF and HIF-1α mRNA expression was analyzed in myocardial samples from patients with ischemic (ICM) and non-ischemic cardiomyopathy (NICM) and from patients after heart transplantation (HTX)." (PMID 29027966, 2017). "To enhance the upregulation of HIF-1α, we administered roxadustat, a novel prolyl hydroxylase inhibitor (PHI) clinically approved by the European Medicines Agency 2021 for the treatment of renal anemia, with the purpose of improving LV function and attenuating ischemic cardiomyopathy." (PMID 38994928, 2024).
kidney injury (5 papers, 2017 to 2026). Trauma to the kidney. "Interestingly, several genes associated with the HIF1α-mediated hypoxia response, which contributes to acute kidney injury and renal IRI, were downregulated in the SNTAP group relative to the SNT group." (PMID 33802753, 2021). "Thus, it is demonstrated that HK2 deficiency-mediated mitophagy inhibition is the critical mechanism in HIF-1α CTAD knockout-induced kidney injury." (PMID 37225700, 2023). "Consistent with our current findings, AhR activation downregulates IRF1 and HIF-1α via miR-142a, which decreases M1 macrophage polarization, increases M2 macrophage polarization, and reduces pro-inflammatory cytokine levels to ultimately protect against CaOx nephrocalcinosis-mediated kidney injury." (PMID 33204326, 2020).
kidney tumors (5 papers, 2007 to 2023). "FH-deficiency may activate the proto-oncogene ABL1 in kidney tumors, which may upregulate aerobic glycolysis via the mTOR/HIF1α pathway, being a promising target marker." (PMID 27556703, 2016). "Taken together, the metabolomics and mRNA expression data indicate that TRACK kidney tumors exhibit glycolysis and lactate production and reduced flux of pyruvate entering the TCA cycle, which is in association with increased expression of HIF1α target genes that mediate the Warburg effect." (PMID 25830305, 2015). "In all renal tumours examined, they noted strong HIF-1α staining in the nuclei of tumour cells." (PMID 17211469, 2007).
liver cirrhosis (5 papers, 2009 to 2024). "Angiogenesis damage to liver blood system in liver cirrhosis and the high proliferation of tumor cells also induces local hypoxia, which was a strong stimulus for HIF-1α." (PMID 23799043, 2013). "If the cutoff value of serum HIF-1α level was > 50 μg/L, the incidence of HIF-1α abnormality was 100% in HCC, 89.2% in liver cirrhosis, 66.7% in chronic hepatitis, and none in acute hepatitis or normal control groups." (PMID 22224081, 2011). "At a cutoff value of 100 μg/L, the abnormality of circulating HIF-1α level was 90.8% in HCC and 27.0% in liver cirrhosis, and none in chronic hepatitis, acute hepatitis, or normal control groups." (PMID 22224081, 2011).
malignant pleural mesothelioma (5 papers, 2014 to 2020). A malignant neoplasm that arises from mesothelial cells in the pleura and shows a diffuse growth pattern. "The HIF-1α-dependent up-regulation of Pgp has been documented in liver, larynx, lung, and breast cancers, as well as in malignant pleural mesothelioma and B-cells chronic lymphocytic leukemia." (PMID 33291643, 2020).
migraine (5 papers, 2023 to 2025). "Under the IVW model, higher plasma HIF‐1α levels were negatively associated with the risk of migraine (OR = 0.941, 95% CI = 0.888–0.998, p = 0.041) and MOAD (OR = 0.586, 95% CI = 0.375–0.916, p = 0.019)." (PMID 40022282, 2025). "Our research indicates a causal inference between plasma HIF‐1α levels and the risk of CES, migraine, and drug‐induced MOA." (PMID 40022282, 2025). "According to our research, elevated plasma levels of HIF‐1α are causally correlated to a decreased incidence of CES, migraine, and drug‐induced MOA." (PMID 40022282, 2025). "We found that genetically predicted higher plasma HIF‐1α levels were associated with CES, migraine, and drug‐induced MOA." (PMID 40022282, 2025). "This study employs a bidirectional MR approach to investigate the causal relationship between the levels of plasma HIF‐1α and the risk of neurological disorders, including IS and its subtypes, SAH, migraines and their subtypes, PD, AD, and ALS." (PMID 40022282, 2025). "The number of monthly migraine headache days was correlated with serum levels of LPS, HIF-1α, VE-cadherin, and IL-6." (PMID 38369488, 2024). "The number of monthly migraine headache days was positively correlated with serum LPS, HIF-1α, VE-cadherin, and IL-6 levels, HADS-A, HADS-D, HIT-6, and MigSCog scores." (PMID 38369488, 2024). "Our research indicated that plasma HIF‐1α may have a causal effect on the risk of CES, migraine and drug‐induced MOA, providing new insights for those disease prevention and therapeutic approaches." (PMID 40022282, 2025). "Migraine duration was positively correlated with serum HIF-1α (r = 0.712, p < 0.0001), and IL-6 levels (r = 0.476, p < 0.0001), HADS-A (r = 0.554, p < 0.0001), HADS-D (r = 0.452, p < 0.0001), and HIT-6 scores (r = 0.505, p < 0.0001) in CM patients with MOH and EM patients." (PMID 38369488, 2024). "Migraine attacks were recently shown to be accompanied by elevated HIF-1α, FGF-21, GDF-15, CGRP, and PACAP-38 in medication-naïve children with migraine." (PMID 38369488, 2024). "Compared with CON group, quantitative real-time polymerase chain reaction showed that PFKP (2.02 ± 0.51), HK2 (2.55 ± 0.72), HIF-1α (3.05 ± 0.61) and PKM2 (1.97 ± 0.49) mRNA expression increased in migraine model group." (PMID 37090989, 2023). "Genetically predicted plasma HIF‐1α was negatively associated with the risk of CES, migraine and drug‐induced migraine without aura." (PMID 40022282, 2025). "In the experimental model of migraine, key enzymes involved in glycolysis such as phosphofructokinase platelet (PFKP), hexokinase (HK2), hypoxia inducible factor-1α (HIF-1α), lactate dehydrogenase (LDH) and pyruvate kinase (PKM2) were expressed in the medullary dorsal horn." (PMID 37090989, 2023). "To explore whether glycolysis increased during the experimental models of migraine, we detected the gene expression of important enzymes related to glycolysis, such as PFKP, HK2, HIF-1α, LDH and PKM2." (PMID 37090989, 2023).
neuroendocrine tumors (5 papers, 2010 to 2023). "Neuroendocrine neoplasms are densely vascularized and express hypoxia-inducible factor (HIF)-1α and vascular endothelial growth factor A (VEGF-A)." (PMID 32156252, 2020). "In neuroendocrine tumor cells, the SSTR2 agonist octreotide reduced intracellular levels of VEGF by decreasing HIF-1α cell content." (PMID 36946182, 2023). "Therefore, we conclude that upregulation of HIF1α as a potential escape mechanism mediating antiangiogenic drug resistance has no relevant impact in neuroendocrine tumors of RIP1Tag2 mice." (PMID 37620408, 2023).
oncocytomas (5 papers, 2014 to 2019). "We here exploit a fine-tunable system of CI ablation in different cancer types to trigger conversion to oncocytomas, and demonstrate that HIF-1α destabilization is accountable for such indolent behavior." (PMID 30796225, 2019). "As oncocytic tumors have less HIF1A, this can explain the increased number of mitochondria in oncocytomas." (PMID 29285300, 2017). "Despite the lack of HIF-1α and lower tumorigenic potential, CI-deficient masses, like oncocytomas, continued to progress, meaning they probably engage alternative, HIF-1α-independent mechanisms to ensure nutrient supply." (PMID 30796225, 2019). "Nonetheless, HIF1α stabilization is usually not a feature of benign oncocytomas, which prompted us to investigate further how such a marker of malignancy may have occurred in this case." (PMID 30728892, 2019). "Interestingly, several cancer-related genes (VHL, HIF1A, cMET, phosphatase and tensin homolog, TSC1, BCL2, BRCA1), which include some tumor suppressors, were also found to be overexpressed in both the benign oncocytoma-like region and the high-grade oncocytic carcinoma region." (PMID 25275525, 2014).
oropharyngeal cancer (5 papers, 2003 to 2025). Carcinoma, predominantly squamous cell, arising from the epithelial cells of the oropharynx. "In oropharyngeal cancer, increased HIF-1α expression promoted relapse after radiotherapy while knocking down HIF1-α enhanced sensitivity towards radiation." (PMID 40272602, 2025).
pancreatic neuroendocrine tumor (5 papers, 2005 to 2026). Pancreatic endocrine tumor, also known as pancreatic neuroendocrine tumor (PNET), describes a group of endocrine tumors originating in the pancreas that are usually indolent and benign, but may have the potential to be malignant. "Previous studies have shown that HIF-1α expression is significantly higher in more aggressive pancreatic NETs than in benign tumours." (PMID 36233825, 2022). "The aim of this study was to establish the expression pattern of VEGF, HIF-1α, HIF-2α and CA9 in a series of pancreatic endocrine tumours and to correlate the level of expression with clinicopathological charateristics, angiogenesis and survival." (PMID 15558070, 2005). "We demonstrate in this study a specific pattern of expression of VEGF, HIF-1α and HIF-2α in pancreatic endocrine tumours." (PMID 15558070, 2005). "This study uncovers a previously unrecognized hypoxic-immune axis in pancreatic neuroendocrine tumors (PNETs), wherein HIF isoform imbalance (HIF-1α/β up regulation, HIF-2α down regulation) drives metastatic dissemination through immune suppression and metabolic rewiring." (PMID 41531732, 2026).
proliferative diabetic retinopathy (5 papers, 2012 to 2025). Advanced retinopathy due to diabetes mellitus characterized by the formation of new vessels in the retina. "According to recent research, HIF1A antisense RNA 2 (HIF1A-AS2), the antisense transcript of HIF-1, is strongly and positively linked with HIF-1α and VEGF and is higher in peripheral blood in NPDR patients as well as in those with proliferative diabetic retinopathy (PDR)." (PMID 38390204, 2024).
synovitis (5 papers, 2021 to 2025). Inflammation of a synovial membrane. "Dysfunction in PRG4 signaling, demonstrated by lower tissue levels of PRG4 along with higher CD44, XO and HIF-1α, was associated with high-grade synovitis." (PMID 41282165, 2025). "A similar pattern for XO and HIF-1α staining was also observed, where high-grade synovitis specimens had stronger staining for XO (p < 0.001) and HIF-1α (p < 0.0001) compared to low-grade synovitis specimens." (PMID 41282165, 2025). "Synovitis increases oxygen consumption in OA, resulting in lower-than-normal oxygen levels in the joint fluid and articular cartilage and increased HIF-1α expression." (PMID 40168275, 2025). "Additionally, synovitis induces angiogenesis in OA, increasing blood flow from the subchondral bone and disrupting the cartilage matrix, further increasing oxygen levels and HIF-1α expression." (PMID 40168275, 2025). "Therefore, we inferred that there might be a HIF-1α-GLUT1-AGEs-HIF-1α loop in DM-induced synovitis, which aggravates the progression of OA." (PMID 34759325, 2021). "Overall, high-grade synovitis specimens were more likely to have lower PRG4 content, along with higher CD44, XO and HIF-1α contents compared to low-grade synovitis specimens." (PMID 41282165, 2025). "Supporting this involvement is that the expression of XO and HIF-1α trended in the same direction as CD44, where in tissues with high-grade synovitis, we observed stronger XO and HIF-1α staining, while absent in normal tissues." (PMID 41282165, 2025).
tendinopathy (5 papers, 2015 to 2025). "Following tendon injury, there is an increase in the levels of hypoxia-associated genes; therefore, an increase in HIF-1α expression is now considered a biomarker of early tendinopathy." (PMID 38247510, 2024). "Samples from human rotator cuff tendons in the early stages of tendinopathy exhibit signs of hypoxia, including upregulation of HIF1α." (PMID 40855996, 2025). "In tendinopathy, due to elevated hypoxia, HIF-1α expression is upregulated, leading to the promotion of neo-angiogenesis." (PMID 38247510, 2024). "HIF-1α has been found to be upregulated in tendinopathy, and previous studies have suggested that HIF-1α inhibition can alleviate tendinopathy symptoms." (PMID 38247510, 2024). "We propose that tendinopathy is an alarmin-mediated pathology initiated and propagated in part by increased expression of HIF-1α." (PMID 28761710, 2017). "We suggest that these three insults, inhibition of prolyl and lysyl dioxygenases, reduction of P4HA1 and LH1 mRNA levels, and reduced tendon vascularization upon HIF-1α depletion, together account for FQ-induced tendinopathies." (PMID 26205818, 2015). "Researchers have observed that HIF-1α overexpression during tendinopathy promotes VEGF expression." (PMID 38247510, 2024). "During tendinopathy, hypoxia promotes the expression of HIF-1α, NOX1, and NOX4." (PMID 38247510, 2024). "Millar and colleagues also reported an increase in HIF-1α levels in tendinopathy samples, which may promote the expression of pro-inflammatory cytokines and various MMPs, disturbing ECM homeostasis and leading to degeneration." (PMID 38247510, 2024). "The manipulation of BNIP3 expression following HIF-1α upregulation may be a potential treatment for tendinopathy." (PMID 38247510, 2024). "Specifically, S100A9 and HIF-1α may have pro-inflammatory effects in tendon disease, nuclear IL-33 may be protective against pro-inflammatory stimuli and HMGB1 may have a potential role in tendon healing." (PMID 28761710, 2017). "This study investigates protein expression in diseased tendon tissues before and after treatment and reveals pro-inflammatory roles for HIF-1α and S100A9 in tendinopathy." (PMID 28761710, 2017).
uterine fibroids (5 papers, 2009 to 2026). "FH-deficient uterine leiomyomas tumors undergo the impairment of oxidative phosphorylation and metabolic shift to aerobic glycolysis and the increase of HIF-1α, contributing to the oncogenic growth of FH-deficient cells." (PMID 35163394, 2022). "In uterine fibroids (leiomyomas), these HIF-1α-dependent processes intersect with steroid hormone signaling, growth factor pathways, inflammatory mediators, and redox imbalance, together promoting tumor persistence and progressive fibrosis." (PMID 42181792, 2026).
abscess (4 papers, 2010 to 2024). An inflammatory process characterized by the accumulation of pus within a newly formed tissue cavity which is the result of a bacterial, fungal, or parasitic infection or the presence of a foreign body. "Massive abscess formation was also detected in H&E staining and HIF-1α positive nuclei were most abundant in the abscess-surrounding areas." (PMID 20644645, 2010). "Additional hinokitiol in the calcium-hydroxide-based dental canal sealers might improve COX-2-associated inflammation, HIF-1α-associated inflammation, and LOX-associated S. aureus abscess formation potentials in vitro." (PMID 24915566, 2014). "Furthermore localized treatment with a drug that stabilized HIF-1α led to a decrease in proliferation of the skin pathogens, Pseudomonas aeruginosa and Acinetobacter baumanii, in a mouse abscess model." (PMID 24367256, 2013). "Our data suggest that TRPA1 influences both DAG and PI3K, resulting in the expected reduction of HIF1α activation, alteration in glycosaminoglycan metabolism, and ultimately worsened MRSA control due to altered abscess formation." (PMID 39337422, 2024). "Our findings further elucidate the potential mechanisms of the established connection between HIF1α and DAG by suggesting that one consequence of this pathway includes modulations of the glycosaminoglycans, which are important precursors of abscess formation." (PMID 39337422, 2024). "HIF1α, through interactions with HSP, induces cell growth and oxygen metabolism, which influences the production of the types of glycosaminoglycans known to aid in abscess formation." (PMID 39337422, 2024).
AIDS (4 papers, 2018 to 2024). A syndrome resulting from the acquired deficiency of cellular immunity caused by the human immunodeficiency virus (HIV). "This study also showed an increased risk of systemic AIDS-NHL with the presence of the T allele in rs2057482, which creates a binding site for miR-196-a2 in the HIF1A 3′-UTR (OR [95% CI] = 1.73 [1.12–2.67])." (PMID 30818878, 2019). "Targeting HIF-1α may represent a viable therapeutic approach for mitigating kidney damage in autoimmune disorders, including AIDs." (PMID 39575238, 2024). "The influence of low oxygen and HIF-1α may vary across the stages of AIDs, facilitating the assessment of disease severity and progression by monitoring alterations in these biomarkers." (PMID 39575238, 2024). "Collectively, these findings suggest that inhibiting metabolic reprogramming of macrophages and downregulating HIF-1α expression in the hypoxic microenvironment may represent viable therapeutic strategies for alleviating tissue inflammation in patients with AIDs." (PMID 39575238, 2024). "Consequently, strategies aimed at modulating HIF-1α to ameliorate local hypoxic conditions may hold significant therapeutic potential for patients with AIDs." (PMID 39575238, 2024). "This study reveals JNK/COX-2/HIF-1α axis activation enhances glycolysis, promoting M1 polarization in HIV-1–infected macrophages, offering a novel approach to AIDS-related inflammation." (PMID 37798121, 2023).
Airway obstruction (4 papers, 2012 to 2025). Obstruction of conducting airways of the lung. "Here, we aimed at investigating the potential involvement of Hif1-α in myeloid cells in horse with recurrent airway obstruction." (PMID 22621400, 2012).
alcohol (4 papers, 2017 to 2026). "Overall, this suggests that astrocyte cell death in either uncomplicated alcoholism or in conjunction with TD may centralize with a HIF-1α mediated transcriptional response and up-regulation of pro-apoptotic/inflammatory genes." (PMID 29045486, 2017).